GPX4 (glutathione peroxidase 4)
Diseases named in the same sentence as GPX4 in open-access papers (continued):
Sharing a sentence is not in itself a finding about the gene and the disease.
cancer (continued). "It has recently been shown that GPX4 activity was decreased in a number of cancer cells treated with erastin." (PMID 37996827, 2023). "In cancer cell lines, knocking down GPx4 expression using RNAi induced ferroptotic cell death, which validated the mechanism of action for RSL3‐induced ferroptosis." (PMID 36595221, 2023). "The pharmacological targeting of FSP1 can exert strong synergistic effects with GPX4 inhibitors, thereby triggering ferroptosis in many individuals with cancer." (PMID 38161691, 2023). "In the CCK-8 assay, we observed that GPX4 overexpression promoted cancer cell growth, which was inhibited by low levels of SGK2." (PMID 36720852, 2023). "The depletion of GPX4 renders cancer cells vulnerable to ferroptosis and the therapy-resistant state of cancer cells is dependent on GPX4 being able to escape multiple therapy challenges." (PMID 37325669, 2023). "Selenium is required for GPX4 synthesis, and selenium addition to prostate normal/cancer cells increases GPX4 expression and prevents cellular oxidative stress." (PMID 37061523, 2023). "This process was due to the interaction of miR-324-3p with GPX4, which led to the downregulation of GPX4 and as a result, mediated the anti-cancer effect by promoting ferroptosis." (PMID 38002073, 2023). "GPX4 is a promising target that can reduce complex lipid peroxides and ferroptosis-kill clinically resistant cancer cells." (PMID 37598126, 2023). "Bufotalin induces cancer cell ferroptosis by promoting GPX4 cellular degradation and increasing intracellular Fe2+ content." (PMID 37833746, 2023). "Combination therapies targeting FSP1 and GPX4, as well as immune checkpoint inhibitors, offer promising avenues for enhancing therapeutic outcomes in cancer treatment." (PMID 37371948, 2023). "Survival analysis revealed notable differences between GPX4 high- and low-expression groups for several cancer types; patients with high-GPX4 expression levels had significantly shorter OS than those with low-GPX4 expression in the TCGA-COAD cohort." (PMID 38065948, 2023). "Proteomic analysis has shown that overexpression of GPX4 in cancer cells can suppress iron dependent death mediated by the transcription factor RSL3, while GPX4 deficiency increases cellular sensitivity to iron dependent death." (PMID 38028615, 2023). "In 54 pairs of COAD and normal tissues, GPX4 was more significantly expressed in cancer tissues than in the normal tissues." (PMID 38065948, 2023). "NRf2 can also directly or indirectly regulate the expression and function of GPX4 to regulate the sensitivity of cancer cells to ferroptosis." (PMID 37007068, 2023). "A recent study has revealed that GPX4, a phospholipid hydroperoxide glutathione peroxidase, promotes ferroptosis, thereby promoting cancer growth." (PMID 37375197, 2023). "Apart fromcombination with reagents that induce the Fenton reaction to enhanceferroptotic cell death, AIEgens can also trigger specific organelleoxidative stress to sensitize cancer cells to GPX4 inhibitors throughan amplified ferroptosis pathway." (PMID 37486125, 2023). "The enhanced PUFA-PL levels in MM cells can detoxify lipid peroxides dependent on GPX4 for survival, leading to the high vulnerability of these cancer cells to ferroptosis." (PMID 37795022, 2023). "Radiation-induced lipid peroxidation can trigger ferroptosis in several cancer types and act in synergy with ferroptosis inducers such as system XC– inhibitor erastin and GPX4 inhibitor RAS-selective lethal 3 (RSL3)." (PMID 37714846, 2023). "Through the public databases, we found that the expression of GPX4 in normal tissues was lower compared with cancer tissues in CRC, and the high GPX4 expression predicted a poor prognosis." (PMID 37658132, 2023). "Altretamine can enhance ROS accumulation and induce cancer cell ferroptosis by inhibiting GPX4 activity." (PMID 37833746, 2023).
cancer (continued). "Glutathione peroxidase 4 (GPX4) has emerged as a promising therapeutic target for cancer therapy, but some cancer cells are resistant to ferroptosis triggered by GPX4 inhibition." (PMID 36617563, 2023). "FSP1 operates independently of the canonical system xc–/glutathione peroxidase 4 pathway, making it a promising target for inducing ferroptosis in cancer cells and overcoming ferroptosis resistance." (PMID 37371948, 2023). "In pan-cancer analysis, we found that GPX4 showed remarkably upregulated expression and exhibited significant association with overall survival in multiple cancer types, especially COAD." (PMID 38065948, 2023). "Comprehensive analysis of the TCGA and Oncomine databases revealed that GPX4 was more highly expressed in most cancers, such as COAD, STAD, LIHC, ESCA, and KIRC, than in normal tissues." (PMID 38065948, 2023). "Global pan-cancer gene expression profiling has revealed that GPX4 is highly expressed in most cancer types, including COAD." (PMID 38065948, 2023). "This process is kept in balance by GPX4, which is abundantly expressed in cancer cells, to prevent autonomous ferroptosis." (PMID 37183818, 2023). "The mitochondria-associated coenzyme Q10 (CoQ10) oxidoreductase ferroptosis suppressor protein 1 (FSP1) is discovered as a potent ferroptosis-resistance factor acting in parallel to GPX4 in cancer cells." (PMID 37550282, 2023). "The GPX4 gene was suggested as the direct target of miR-324-3p, and miR-324-3p expression restoration reversed the cancer cells’ sensitivity to cisplatin, again through inducing ferroptosis." (PMID 38002073, 2023). "The ferroptosis inhibitory gene solute carrier family 7 member 11 (SLC7A11) and glutathione peroxidase 4 (GPX4) inhibit ferroptosis in carcinoma cells." (PMID 37807410, 2023). "DHA significantly reduces GPX4, while maintaining ACSL4 and xCT system activity, increases ferroptosis and causes cancer cell death." (PMID 35208642, 2022). "For example, GPX4, as a negative regulator of iron apoptosis, plays a major antioxidant role in anti-cancer activity and the inhibition of GPX4 can enhance ferroptosis and thus enhance the sensitivity of CRC to cisplatin/oxaliplatin." (PMID 35740594, 2022). "Studies have identified that FSP1 confers resistance against ferroptosis upon treatment with GPX4 or xc-system inhibitors in vitro and in vivo, and its depletion can elevate lipid peroxide levels in cancer cells." (PMID 35805884, 2022). "Induction of ferroptosis emerged as a new strategy to trigger cancer cell death and ferroptosis-inducing compounds have been categorized into two classes based on their inhibition mode of Glutathione Peroxidase 4 (GPX4)." (PMID 36059648, 2022). "There are few studies that suggest that the role of GPX4 in human cancer is complex and paradoxical." (PMID 36443446, 2022). "The triggering of ferroptosis by the inhibition of GPX4 has been recognized as a treatment approach to initiate cancer cell death." (PMID 35620733, 2022). "This approach has shown its efficacy by discovering the dependency of GPX4 in mesenchymal-like and/or drug-persistent cancer cells." (PMID 36672609, 2022). "Lipid hydroperoxides are neutralized in cells by glutathione peroxidase 4 (GPX4) and inhibitors of GPX4 are potent ferroptosis inducers with therapeutic potential in cancer." (PMID 35523770, 2022). "More evidence has shown that ferroptosis inducers, such as erastin, can synergistically promote the anticancer effect of cisplatin by antagonizing system Xc‐ or GPX4 in a variety of cancers." (PMID 36317423, 2022). "ML210 kills cancer via induction of ferroptosis through covalent interactions with its target, GPX4." (PMID 35581546, 2022). "HIF2α inhibits GPX4 expression and drives PUFA remodeling by activating hypoxia-induced lipid droplet-associated (HILPDA), causing cancer cells to be highly sensitive to ferroptosis." (PMID 35911967, 2022).
cancer (continued). "Inactivation of SLC7A11 or GPX4 with ferroptosis inducers is able to sensitize radioresistant cancer cells and xenograft tumors to IR." (PMID 35847022, 2022). "Altretamine is an FDA-approved anti-cancer drug for the treatment of ovarian cancer, which induces ferroptosis through GPX4 inhibition." (PMID 34996454, 2022). "Resistance to ferroptosis is achieved by turning the cancer cell into a selenophillic environment to promote the uptake of Se and Sec, which leads to upregulation of glutathione peroxidase 4 (GPX4), a key endogenous ferroptosis inhibitor." (PMID 36358931, 2022). "The anti-ferroptotic activity of vitamin K was not only limited to mouse fibroblasts, as it also prevented ferroptosis in the human cancer cell lines A375 and 786-O that lack GPX4 expression." (PMID 35922516, 2022). "Cancer cells exhibit higher ROS levels compared to normal cells, and this leads to higher expression of NOXs and GPX4." (PMID 36072803, 2022). "A recent report indicated that Gpx4 contributes to maintaining the stemness phenotype of cancer stem-like cells." (PMID 35681465, 2022). "The utilization of SLC7A11 to uptake Sec instead of cysteine facilitates the synthesis of selenoprotein GPX4 by cancer cells." (PMID 36358931, 2022). "To date, there are at least three pathways that mediate ferroptosis in cancer cells: system Xc-/GSH/GPX4, FSP1/CoQ10/NAD(P)H, and ATG5/ATG7/NCOA4." (PMID 36009223, 2022). "The enhanced synthesis of PUFA‐PL in these cancer cells makes them strongly dependent on GPX4 to detoxify lipid peroxides for survival." (PMID 36317423, 2022). "Supplementation with DHO or OA(substrates and products of DHODH) attenuated and enhanced GPX4-induced iron death, respectively, especially in cancer cells with low GPX4 expression." (PMID 36309489, 2022). "Further in vivo experiments also showed that the silencing of GPX4 enhanced the anti-cancer effect of lapatinib by promoting ferroptosis." (PMID 36105219, 2022). "As a potent ferroptosis inducer, it promotes ferroptosis in cancer cells by directly inhibiting GPX4." (PMID 35847022, 2022). "This trend was also found in the Cancer Cell Line Encyclopedia metabolomics analysis, which demonstrated that the abundance of PUFAs was the most correlated with the genetic dependency on GPX4." (PMID 35581546, 2022). "Previous studies reported that high mesenchymal therapy-resistant persister cancer cells are vulnerable to GPX4 inhibition and ferroptosis induction." (PMID 35402284, 2022). "First, accumulation of H2Se formed during Sec decomposition is toxic to cancer cells as it increases ROS with these cells, therefore, relying on GPX4 to neutralize selenide-induced ROS." (PMID 36358931, 2022). "The pathway p62–NRF2 was shown to be involved in the resistance of cancer cells to ferroptosis under GPX4 inhibition." (PMID 35954245, 2022). "FSP1 expression positively correlates with cancer cell resistance to ferroptosis induced by GSH depletion or GPX4 inhibition." (PMID 36505465, 2022). "For example, gemcitabine can increase the expression level of heat shock protein 70 family protein 5 (HSPA5), thereby preventing the degradation of the GPX4 protein and ferroptosis in cancer cells." (PMID 36317423, 2022). "Breast and other cancer cells are selenophilic, allowing production of selenoproteins such as GPX4, protects cells against ferroptosis." (PMID 36105219, 2022). "FSP1 was observed to be capable of compensating for GPX4 deletion to inhibit ferroptosis in cancer cells." (PMID 35013137, 2022). "Although multiple genes, such as ACSL4, PTGS2, NOX1, GPX4, FTH1, and SLC7A11, have been shown to be associated with ferroptosis, it is unclear how ferroptosis is genetically programmed in cancers." (PMID 35321435, 2022). "We found that Zn2+ or Zn-Fu MNs treated groups showed the higher level of LPOs, owing to the ROS production and GPX4 inactivation within those cancer cells induced by free Zn2+ or Zn-Fu MNs." (PMID 36168615, 2022).
cancer (continued). "An elegant study showed that intracellular fumarate aggregation led to the succination of GPX4 at cysteine 93 (mono- and di-succination), which significantly reduced the enzymatic activity of GPX4 and sensitized cancer cells to FINs." (PMID 35647032, 2022). "Inhibition of SLC7A11 or GPX4 induces resensitization of radiation-resistant cancer cells to IR-induced ferroptosis, leading to radiosensitization." (PMID 36072803, 2022). "Inhibition of xCT and GPX4 can induce cancer cell death to conventional chemotherapy or radiotherapy." (PMID 35847022, 2022). "NUAK2 expression correlated with sensitivity to GPX4 inhibitors across a variety of human cancer cell lines." (PMID 35523770, 2022). "This glutathione system is critical for protecting cancer cells against ferroptosis-dependent death via the detoxification activity of GPX4 for reducing lipid peroxides into their alcohols using GSH as a cofactor." (PMID 36686682, 2022). "In cancer treatment, GPX4 modulation via influencing ferroptosis plays a crucial role in cancer cell death." (PMID 35208642, 2022). "Given the expression of GPX4 in other cancer types, its oncogenic function also highlights its potential as a therapeutic target for cancer treatment." (PMID 35105963, 2022). "As classical inducers of ferroptosis, erastin and RSL3, which inhibits system xc- and glutathione peroxidase 4 (GPX4), respectively, are being widely explored as potential therapeutics various types of cancer cells." (PMID 36130940, 2022). "After supplementation with DHO or OA (the substrate and product of DHODH), the ferroptosis caused by GPX4 inhibition was attenuated and enhanced, respectively, and these effects were particularly significant in cancer cells with low GPX4 expression." (PMID 36309489, 2022). "While GPX4 is expressed in most cancer cell lines, it is essential for various organs, including kidneys and neurons." (PMID 35422492, 2022). "Cell lines most sensitive to GPX4 inhibitors had significantly higher NUAK2 expression compared to resistant cell lines (p < 0.00001, Student’s t-test), supporting an association across cancer types between NUAK2 and GPX4 inhibitor sensitivity." (PMID 35523770, 2022). "From a therapeutic perspective, FSP1 appears to be a better therapeutic target than GPX4 in cancer treatment, as inhibiting FSP1 presumably would cause less toxicities in normal tissues than would inhibiting GPX4." (PMID 35459868, 2022). "We focus here on how the Se metabolism influences cancer metabolism via GPXs aside GPX4, which has been discussed in the previous section." (PMID 36358931, 2022). "A role for myeloid cell–expressed Gpx4 in host resistance to infection and cancer has been documented in many previous studies involving different mechanisms and outcomes." (PMID 36069923, 2022). "Cancer cell exhibits ability to evade ferroptosis by activation of antioxidant signaling pathways such as SLC7A11/GPX4 axis." (PMID 36289191, 2022). "In nucleus, NRF2 forms a heterodimer with sMaf and binds to ARE, protecting cancer cells from GPX4 inhibition and promoting the transcription of antioxidant enzymes, such as HMOX1, NOQ1, and GSTS, reducing ROS levels, forming resistance to ferroptosis." (PMID 36505465, 2022). "In cancers that display resistance towards common therapeutic strategies and are highly metastatic, GPX4 and NRF2, two factors influencing ferroptosis negatively, seem to drive cancer resistance." (PMID 35406596, 2022). "The FSP1–CoQ10–NAD(P)H pathway existed as an independent parallel system, which cooperated with GPX4 and glutathione to suppress ferroptosis in a number of cancer cells." (PMID 35311093, 2022). "The effects of solasonine on glutathione metabolism, including GPX4 as well as glutathione synthetase (GSS), and inhibition of GPX4-induced ferroptosis are effective therapeutic strategies for triggering cancer cell death." (PMID 35494004, 2022).
cancer (continued). "These regulatory mechanisms of GPX4 level/activity have already shown a great potential for treating ferroptosis-related diseases in preclinical studies, especially in cancer cells." (PMID 35647032, 2022). "The change in oxidative state in the active site of GPX4 as a consequence of an amino acid change suggests that a steady Se supply is vitally necessary for the production of GPX4 in cancer cells, and their consequent resistance to peroxide-induced ferroptosis." (PMID 36358931, 2022). "Inspired by the efficient ferroptosis induced by Zn-Fu MNs in cancer cells, we explored the GPX4 protein activity and LPO level mediated by Zn-Fu MNs in vivo." (PMID 36168615, 2022). "We found that the mRNA expression level of PRKACA was higher in the normal cell line than in the cancer cell lines, and for GPX4 it was the opposite, consistent with our results above." (PMID 35646872, 2022). "Inactivation of DHODH in cancer cells with low GPX4 expression significantly increased intracellular lipid peroxidation, while in cancer cells with high GPX4 expression, DHODH inactivation synergized with inducers to enhance ferroptosis." (PMID 36309489, 2022). "The influence of GPX4 on cancer prognosis agreed with that of FAP, indicating a significant relationship between FAP and ferroptosis." (PMID 35359436, 2022). "It is well established that GPX4 is an attractive specific target for new pharmacological therapeutics aiming at activating cell death in cancer or inhibiting cell death in degenerative diseases." (PMID 35453641, 2022). "Inhibition of System xc− can effectively downregulate GSH/GPX4 expression, thereby inducing cancer cell ferroptosis." (PMID 36052168, 2022). "There are numerous ways to achieve the induction and modulation of ferroptosis, such as the depletion of intracellular glutathione (GSH) 14, the inactivation of glutathione peroxidase 4 (GPX4) 15, and the excessive delivery of iron into cancer cells." (PMID 34976215, 2022). "In our study, we observed that H. pylori leads to the high antioxidant status of cancer cells by upregulating GPX4 expression and activity via TCF4." (PMID 35534546, 2022). "Compared with the differential expression of mitochondrial-localized GPX4 in different cancer cell lines, DHODH is ubiquitously expressed." (PMID 36238649, 2022). "FSP1 was identified in genetic screens from two independent research groups that sought to determine pathways that govern resistance to GPX4 inhibition-induced ferroptosis in cancer lines." (PMID 35065965, 2022). "It is triggered by the accumulation of iron in cells with decreased levels of glutathione peroxidase (GPX4), increased levels of ROS, and membrane lipid peroxidation reactions that damage cell and mitochondrial membranes, leading to cancer cell death." (PMID 35392237, 2022). "For example, it has been confirmed that the expression of the GPX4 gene is beneficial to the survival of cancer cells in a state of high mesenchymal therapy drug resistance." (PMID 34975326, 2022). "Cancer cells with mesenchymal phenotype are highly dependent on GPX4 and are abundant in polyunsaturated fatty acids due to the elevated levels of ZEB1, ELOVL5, and FADS1 expression." (PMID 36335094, 2022). "GPX4 can reduce phospholipid hydroperoxide to hydroxy phospholipid, thus inhibiting ferroptosis in cancer cells." (PMID 35242169, 2022). "LRP8 is required for selenium uptake in cells and promotes resistance to ferroptosis in cancer cells due to the expression of GPX4." (PMID 36008942, 2022). "The existing ferroptosis-inducing drugs (such as erastin and RSL3) that rely on GPX4 inhibition are only effective on a small portion of cancers, due to the limited lipid ROS generation." (PMID 36517470, 2022).